CX3CL1 (C-X3-C motif chemokine ligand 1)
Diseases named in the same sentence as CX3CL1 in open-access papers (continued):
Sharing a sentence is not in itself a finding about the gene and the disease.
colitis (9 papers, 2014 to 2025). Inflammation of the colon. "One study showed that loss of CX3CR1 or its ligand CX3CL1 rendered mice less susceptible to experimentally induced colitis." (PMID 32987848, 2020). "In contrast, another more recent study showed that CX3CR1 and CX3CL1 were highly upregulated in the colon during experimentally induced colitis and that Cx3cl1-deficient mice and two different strains of Cx3cr1-deficient mice developed more severe colitis as compared to controls." (PMID 32987848, 2020). "Of note, DSS-induced colitis mouse model was constructed to demonstrate that the expression of key anoikis genes, namely H2-DMa, CX3CL1, and CFB were significantly upregulated, while PDK4 was evidently downregulated." (PMID 40115777, 2025). "CX3CL1 was recently observed in the colon of IBD patients and Oxa-treated mice, whereas the use of anti-CX3CL1 mAb can significantly improve colitis symptoms by dislodging the crawling monocytes and repressing leukocyte activation and infiltration." (PMID 36831001, 2023). "Additionally, allocryptopine improved the intestinal barrier and reduced the colitis response by inhibiting CX3CL1/GNB5/AKT2/NF-κB/apoptosis pathway." (PMID 37446938, 2023). "Increased CX3CL1/CX3CR1 in human and mouse models suggested that it could be a potential biomarker for colitis, and V249I polymorphism of the CX3CR1 gene is associated with intestinal strictures, particularly in smokers in CD patients." (PMID 37994325, 2023). "The protective effect of MMP-19 over colitis seems to originate from its capacity to control neutrophils and macrophage migration to wounded mucosa, possibly through the processing of the chemokine domain of fractalkine (CX3CL1)." (PMID 33802197, 2021).
interstitial lung disease (9 papers, 2012 to 2025). A diverse group of lung diseases that affect the lung parenchyma. "In fibrosing interstitial lung diseases, CX3CL1 establishes concentration gradients within the pulmonary microenvironment that drive the recruitment of these non-classical monocyte populations." (PMID 40650314, 2025). "Elevated levels of CX3CL1 in SSc correlate with interstitial lung disease progression, indicating its potential as a serological marker for skin and pulmonary complications in SSc patients." (PMID 39392260, 2024). "Higher levels of CX3CL1 were correlated with the severity of interstitial lung disease in SSc patients, indicating a potential predictive marker for disease progression." (PMID 39392260, 2024). "The correlation between increased CX3CL1 levels in SSc‐interstitial lung disease (ILD) was established." (PMID 39392260, 2024). "The CX3CL1/CX3CR1 axis has also been associated with driving a proinflammatory phenotype in disease settings, and administration of an anti-CX3CL1–neutralizing antibody in a model of interstitial lung disease resulted in a decrease of an M1-described inflammatory macrophage infiltration." (PMID 38618956, 2024). "The second study was performed on 83 patients with interstitial lung disease (ILD), who had increased CX3CL1 levels in plasma and lung tissue." (PMID 33391453, 2021). "We explored CX3CL1 in systemic sclerosis (SSc) related progressive interstitial lung disease (ILD) and pulmonary hypertension (PH) in two different but complementary sources of biomaterial." (PMID 30457999, 2018). "Using in vitro migration assays it was also found that recombinant CX3CL1 drives the migration of non-classical monocytes in patients with interstitial lung disease." (PMID 33391453, 2021). "In this study, we retrospectively analyzed the expressions of CX3CL1/fractalkine and its corresponding receptor, CX3CR1, in muscle and lung with interstitial lung disease (ILD) of PM patients and DM patients, and determined the correlation between serum soluble CX3CL1 level and disease activity." (PMID 22394569, 2012). "Therefore, we investigated the effects of an anti-CX3CL1 monoclonal antibody (mAb) on immune-mediated interstitial lung disease (ILD) in SKG mice, which exhibit similar pathological and clinical features to human RA-ILD." (PMID 34067842, 2021).
endometriosis (8 papers, 2018 to 2025). The growth of functional endometrial tissue in anatomic sites outside the uterine body. "It has been established that CX3CL1 levels in PF and endometrial stromal cells (ESCs) are associated with the progression of endometriosis and invasiveness of ESCs." (PMID 36008949, 2022). "Another important mediator for neuropathic pain exhibited in endometriosis patients is via fractalkine (CX3CL1)." (PMID 36008949, 2022). "This suggests that this chemokine is essential for the development and progression of neuropathic pain in endometriosis and future studies could focus on targeting CX3CL1 to relieve persistent-neuropathic endometriotic pain." (PMID 36008949, 2022). "Moreover, chemokine fractalkine CX3CL1 and its receptor CX3CR1 are upregulated in ectopic endometrium and they are involved in endometriotic pain conduction, based on the results of the endometriosis animal model." (PMID 33435569, 2021). "Moreover, the CXC chemokine family and CXC chemokine receptors, along with chemokine fractalkine CX3CL1 and its receptor CX3CR1, have also been highlighted for their contribution in the development of the local inflammatory milieu and the formation of the peripheral hyperalgesia in endometriosis." (PMID 33435569, 2021).
multiple myeloma (8 papers, 2016 to 2025). "The CX3CL1/CX3CR1 axis has been previously implicated in the interaction between multiple myeloma cells and the bone microenvironment, and also associated with cell survival and disease progression." (PMID 32211606, 2020). "ChIP-on-chip data revealed that heparanase bound to regulatory regions of myeloma-related genes (i.e., CXCL12), encodes for SDF-1, CXCR4, CXCL2, CXCR3, CCL27, CX3CL1, and LCN2." (PMID 36980254, 2023). "Among them, CX3CL1 is the most prevalent and has recently been discovered as a pro-angiogenic factor in myeloma patients." (PMID 37875556, 2023). "In particular, the CX3CL1/CX3CR1 axis supports cooperation between multiple myeloma and osteoclast cells to promote adhesion of MM cells to bone extra cellular matrix (ECM), which is a required process for disease progression." (PMID 32211606, 2020). "Conditioned medium from CX3CL1-stimulated RPMI-8226 human multiple myeloma cell line induced the differentiation of osteoclasts from precursor cells, which implicates the CX3CL1-CX3CR1 axis in the progression of multiple myeloma through the generation of a niche supporting myeloma cells in the bone." (PMID 33391453, 2021). "The role of the CX3CL1/ C-X3-C motif chemokine receptor 1(CX3CR1) axis in the multiple myeloma (MM) microenvironment is still unknown." (PMID 30845779, 2019). "In other hematological cancers, CX3CR1 and its ligand, CX3CL1, have been proposed to be involved in the interaction between chronic lymphocytic leukemia cells and their microenvironment, and CCR1 has a crucial role in the pathogenesis of myeloma-associated bone disease." (PMID 27258612, 2016). "To unveil the source of the high BM CX3CL1 levels in MM patients, we analyzed CX3CL1 mRNA expression by primary CD138+ cells and human myeloma cell lines (HMCLs) in public datasets (GSE16122) (GSE6205)." (PMID 30845779, 2019).
schizophrenia (8 papers, 2020 to 2026). A major psychotic disorder characterized by abnormalities in the perception or expression of reality. "The present study compares the levels of interleukin (IL)-10, interleukin-8 (CXCL8), and fractalkine (CX3CL1) between schizophrenia patients and healthy controls." (PMID 35782435, 2022). "Hence, further research is required to fully define and explain the involvement of quetiapine and other antipsychotics in Cx3cl1-Cx3cr1 and/or Cd200-Cd200r axes modulation and inflammatory processes in the LPS-based model of schizophrenia-like disturbances." (PMID 36139363, 2022). "The additional acute challenge with LPS later in life, according to the “two-hit” hypothesis of schizophrenia, decreased levels of hippocampal CX3CL1 in rats with altered PPI and cortical CX3CR1 in animals without such behavioral deficiency." (PMID 34021899, 2021). "Following on from these findings regarding the role of immune processes in schizophrenia development the present study evaluates the serum levels of anti-inflammatory cytokine IL-10, and pro-inflammatory chemokines CXCL8 and CX3CL1 in schizophrenic patients." (PMID 35782435, 2022). "To date, only a few studies have evaluated the expression of CX3CL1 and CX3CR1 in patients with schizophrenia." (PMID 34021899, 2021). "For instance, in DBA/2 mice, schizophrenia-related behaviour (expressed as PPI deficit and reduced social interactions) coexists with the down-regulation of Cx3cl1 gene expression in the cortex." (PMID 33557113, 2021). "In the offspring at postnatal day 7 (PND7), we examined the impact of MIA on the mRNA and protein expression of CX3CL1, CD200 and their receptors in the hippocampus and frontal cortex, which are areas of the brain distinctly affected in schizophrenia." (PMID 32829711, 2020). "In the same study, no discrepancies between control subjects and those affected by schizophrenia were found in terms of the transcript expression of neither CX3CL1 nor CX3CR1 in the orbitofrontal cortex." (PMID 34021899, 2021). "Additional analysis of the samples from patients with schizophrenia revealed a subtle but significant negative correlation between CX3CL1 protein level and lifelong antipsychotic dose." (PMID 34021899, 2021).
unstable angina (8 papers, 2013 to 2025). "CX3CR1, (CCL5/RANTES) and CC chemokine ligand-18 (CCL18/ PARC) are closely related to refractory unstable angina and can be used as a specific marker, while CX3CL1 is used as a marker of response to statin therapy." (PMID 31934638, 2019). "Prior studies of CX3CL1 in human subjects showed substantial increases in CX3CL1 serum protein levels in the setting of chronic coronary artery disease and unstable angina." (PMID 24995121, 2014). "Moreover, patients with unstable angina and unstable plaque have shown higher CX3CL1 levels and increased expression of CX3CR1." (PMID 41153665, 2025). "Similarly, FKN/CX3CL1 levels were more elevated in patients with AMI after PCI than in patients with stable angina, but the values equalized after 24 h in both groups." (PMID 38612695, 2024). "While comparing patients with stable and unstable angina, CX3CR1 expression and FKN/CX3CL1 concentration was higher in the latter group." (PMID 38612695, 2024).
Anxiety (7 papers, 2014 to 2025). Intense feelings of nervousness, tension, or panic often arise in response to interpersonal stresses. "High-anxiety behavior (HAB) mice exhibit region-specific microglial remodeling, with increased microglial density in the dentate gyrus (DG) and elevated CX3CL1 levels in the medial prefrontal cortex (mPFC), correlating with anxiety phenotypes." (PMID 40699743, 2025). "Together, these findings suggest that, within 12 h after stress induction, elevated soluble CX3CL1 protein can promote microglial phagocytosis of GABACeA neuronal spines, thereby reducing GABACeA neuronal activity and driving the recovery from anxiety-like behaviors in model mice." (PMID 38200023, 2024). "To examine whether this enhanced soluble CX3CL1 in the CeA is responsible for ARS-induced anxiety-like behaviors, we bilaterally injected the JMS-17-2, or the vehicle control, into the CeA of ARS-2h mice." (PMID 38200023, 2024). "According to this interpretation under normal conditions, CX3CL1 could balance CCL2 and function as an inhibitor of anxiety." (PMID 33192326, 2020). "The combination of alcohol withdrawal and CCL2 knockdown decreased CX3CL1 and may alter pro-inflammatory/anti-inflammatory balance, and thus highlights the potential importance of CCL2 and CCL2/CX3CL1 balance in anxiety." (PMID 33192326, 2020). "Indeed, it was found that the increase in CX3CL1 caused by CCL2 knockdown was completely reversed following withdrawal from alcohol suggesting that the loss of both CCL2 and CX3CL1 below functional levels may be responsible for the increase in anxiety-like behavior in this experimental group." (PMID 33192326, 2020).
autoimmune disease (7 papers, 2019 to 2025). A disorder resulting from loss of function or tissue destruction of an organ or multiple organs, arising from humoral or cellular immune responses of the individual to their own tissue constituents. "A combination of four different proteins: BDNF (Brain Derived Neurotrophic Factor), I-TAC/CXCL11, soluble (s) CD163 and Fractalkine/CX3CL1 was identified as a pSS protein signature as it could discern pSS from other autoimmune diseases." (PMID 35892673, 2022). "Additionally, considering that blocking CX3CL1 has shown efficacy in reducing inflammation in autoimmune disorders and potential for treating RA, it is plausible that targeting CX3CL1 could also have beneficial effects in managing MPA/GPA55." (PMID 38622321, 2024). "Although the importance of the FKN‐CX3CL1/CX3CR1 axis in neurological and autoimmune diseases is well established, little is known about the interaction between CX3CL1 and other CX3CR1 ligands whose expression is also increased in inflammatory processes such as periodontitis." (PMID 38415821, 2024). "CX3CL1, the only member of the CX3C chemokine family, and its sole receptor, CX3CR1, are involved in the recruitment of monocytes/Mφ and lymphocytes, playing crucial roles in various autoimmune diseases." (PMID 39497829, 2024).
brain tumors (7 papers, 2007 to 2020). "For example, increased expression of CX3CL1 gives a poorer prognosis in grade III-IV brain tumors." (PMID 32466280, 2020). "For example, Cx3cl1 is elevated by LPS, HIV infection, as well as in brain tumors, epilepsy, and in other neuropathological conditions." (PMID 31770590, 2020). "Since CXCL16 was able to activate Akt via inverse signaling mechanisms in brain tumors, the PI3K-AKT signaling pathway might be involved in the regulation of VEGFC expression via CXCL16, and probably via CX3CL1, during cellular dormancy exit." (PMID 32346064, 2020). "Early papers demonstrated that the levels of CX3CL1 may be modulated by various toxic stimuli in vitro and that CX3CL1 signaling is positively or negatively regulated in EAE and MS, in HIV infection and LPS challenge, in epilepsy, in brain tumors, and in other neuropathologies." (PMID 25152714, 2014).
cognitive decline (7 papers, 2022 to 2026). "Age-associated reductions in CX3CL1 exhibit a strong correlation with cognitive decline; administration of exogenous CX3CL1 partially mitigates these deficits." (PMID 41669249, 2026). "We found significant evidence to support an association between CX3CL1 and neurogranin, already in the early stages of cognitive decline." (PMID 37685973, 2023). "Further longitudinal studies are essential to elucidate the temporal changes in CX3CL1 levels across different stages of cognitive decline and to explore its predictive value in identifying individuals at risk of developing AD." (PMID 39917031, 2025). "While urinary CX3CL1 levels decreased with cognitive decline, aMCI had lower urinary CX3CL1 levels than cognitively normal elderly subjects." (PMID 39917031, 2025). "While further studies are required to elucidate the precise role of the adipose CX3CL1-mediated regulation of BDNF expression, studies on white adipose tissue may provide new therapeutic targets for preventing age-associated cognitive decline." (PMID 40724847, 2025). "Levels of soluble CX3CL1 correlate with cortical synapse density, and cerebrospinal fluid concentrations predicting cognitive decline over three-year period in the ENCORE-HD trial cohort, positioning CX3CL1 as both a biomarker and a therapeutic target." (PMID 40699743, 2025).
diabetic retinopathy (7 papers, 2015 to 2025). "Studies of CX3CR1-KO and CX3CL1-KO mice reveal that a disrupted CX3CR1/CX3CL1 signaling pathway exacerbates diabetic retinopathy damage through microglial activation, neuronal cell loss, and vascular impairment." (PMID 39940727, 2025). "In diabetic retinopathy, the ADAM17-mediated cleavage of CX3CL1 and VCAM-1 in retinal endothelial cells has been associated with vascular leakage and retinal neovascularization." (PMID 37762417, 2023). "CD40 and TNF-α are also central to the development of diabetic retinopathy while CX3CL1 may play a role in the pathogenesis of this retinopathy." (PMID 26710229, 2015).
epilepsy (7 papers, 2014 to 2025). A brain disorder characterized by episodes of abnormally increased neuronal discharge resulting in transient episodes of sensory or motor neurological dysfunction, or psychic dysfunction. "In this paper, we review literature updates and summarize the current knowledge about the opposing role of the CX3CL1/CX3CR1 signaling pathway in selected neuropathologies (including ischemia, epilepsy, and neurodegenerative diseases)." (PMID 33065974, 2020).
gastric adenocarcinoma (7 papers, 2017 to 2024). "On the one hand, the CX3CL1/CX3CR1 signaling transduces antitumor effects going along with a better prognosis for the patient like in hepatocellular, gastric adeno carcinoma." (PMID 29867042, 2018). "On the other hand, fractalkine (CX3CL1), a CX3C chemokine, could enhance the recruitment of NK cells and induce both innate and adaptive immunity, thereby yielding a better prognosis in gastric adenocarcinoma." (PMID 30719024, 2018).
Hyperglycemia (7 papers, 2016 to 2025). An increased concentration of glucose in the blood. "According to array gene expression analysis, CX3CL1/CX3CR1 was consistently markedly elevated in human endothelial cells in hyperglycemia status." (PMID 37928902, 2023). "The study results showed that hyperglycemia-induced CX3CL1 overexpression was significantly reduced by EMT both in vivo and in vitro." (PMID 36310615, 2022). "Alternatively, other studies also demonstrated that hyperglycemia induced upregulation of the C-X3-C motif chemokine ligand 1 (CX3CL1)/C-X3-C motif chemokine receptor 1 (CX3CR1) signaling pathway, which is known to disturb placental perfusion." (PMID 34489862, 2021). "The expression level of fractalkine (CX3CL1) was increased by hyperglycaemia (+48%) and significantly decreased by both urolithins (−33% for UA and −28% for UB)." (PMID 28683791, 2017). "Met therapeutic effects in lowering hyperglycemia in obese people, those with T2DM, or those with impaired glucose tolerance may be mostly linked to decreased TNF-α and CX3CL1 production." (PMID 40088335, 2025). "Interestingly, in light of their results, the authors reported the therapeutic effects of resveratrol on reducing hyperglycemia and reductions in CX3CL1 production." (PMID 37928902, 2023). "We then investigated whether enhanced CX3CL1 expression would persist after hyperglycemia was controlled." (PMID 35370759, 2022). "Moreover, canagliflozin could inhibit hyperglycemia-induced CX3CL1 expression in cardiac and renal cells and improved cardiorenal dysfunction in diabetic mice." (PMID 35370759, 2022). "After hyperglycemia had persisted for 4 weeks, we treated STZ-induced diabetic WT mice and NOD mice with insulin or an CX3CL1 neutralizing antibody for 2 weeks." (PMID 35370759, 2022). "Western blotting revealed that myocardial and renal CX3CL1 protein expression was not significantly lower after the control of hyperglycemia than in the untreated group, suggesting that upregulation of CX3CL1 may represent a molecular memory of hyperglycemia." (PMID 35370759, 2022). "We found that cardiac and renal CX3CL1 protein levels were significantly increased in both streptozotocin-induced diabetic mice and in non-obese diabetic mice, and that hyperglycemia led to persistent CX3CL1 expression in the heart and kidneys even after it was controlled by insulin." (PMID 35370759, 2022).